SDC1 (syndecan 1)
Diseases named in the same sentence as SDC1 in open-access papers (continued):
Sharing a sentence is not in itself a finding about the gene and the disease.
tumor (continued). "However, IGF1-mediated activation of IGF1R is blocked by SSTNIGF1R in the tumor cells, indicating that activation of IGF1R with or without IGF1 in the tumor cells is highly dependent on its linkage to Sdc1." (PMID 36968227, 2023). "Moreover, with the exception of functional breast-cancer–platelet interactions, the interplay of the Sdc-1-TF pathway with additional cell types of the tumor microenvironment was not evaluated in our experimental setup." (PMID 36980251, 2023). "Furthermore, the observation that circulating EVs enriched in SDC1 correlated with the expression of SDC1 in matched tumors, and decreased after surgical removal, provided a strong support that SDC1-EV content comes from GBM tumours." (PMID 34205183, 2021). "Additionally, in iCCA, we performed a correlation analysis between the syndecan-1 H-score and the residual tumor classification, the lymph node status, the iCCA subclassification (small and large duct type), and the Ki-67 proliferation rate." (PMID 34206469, 2021). "Thus, the balance between the level of nuclear and non-nuclear heparanase and syndecan-1 shedding potentially provides a mechanism for fine-tuning the expression of multiple genes that regulate tumor behavior." (PMID 32899927, 2020). "Furthermore, the HSPG syndecan-1 was shown to exert an immunomodulatory role on the polarization of CD4+ T helper (Th) subsets isolated from the tumor tissues of patients with inflammatory BC and non-inflammatory BC." (PMID 32847060, 2020). "However, tumor Sdc-1 silencing does not alter the polarization of Th cells towards a particular subset, but increases only the Th1/Treg ratio indicating a skewing of the polarization towards Th1 subset in IBC." (PMID 31145753, 2019). "The absence of host Sdc1 did not affect the Ki67 proliferation index in the primary carcinoma cells, indicating that host Sdc1 does not significantly stimulate 4T1 carcinoma cell proliferation in the primary tumor site." (PMID 29976229, 2018). "In addition, this primary cell cultures were from PCa primary tumor, like 22Rv1 cell line (but this last were immortalized) that neither shown a SDC-1 repression with the ZEB1 over expression." (PMID 30065348, 2018). "Tumor cells express Sdc1 constitutively and as allografts, independent of the mouse host genotype." (PMID 29976229, 2018). "Furthermore, in the 22Rv1 cell line, derived from primary tumor and lacking RAS mutations, no SDC-1 repression by ZEB1 was observed." (PMID 30065348, 2018). "In contrast to SDC1 and SDC2, both SDC3 and SDC4 were undetectable in the healthy epithelium, or the tumour stroma, but could be immunolocalized both subcellularly and on defined portions of the cell surface of neoplastic cells, with a particular concentration in focal plaque-like structures." (PMID 25935541, 2015). "However, other authors reported, despite the reduction of syndecan 1 in high Gleason samples, that this syndecan is not a good predictor for tumor recurrence or survival, reducing its clinical importance as a marker." (PMID 24424718, 2014). "Our analysis of tumor and healthy tissue sections using monoclonal anti-SDC1 displayed an intense Immunoreactivity of the tumoral stroma regardless of the nature of the tumor, although this was more intense in metastatic IDCs, and lesser staining of the basement membrane of ducts." (PMID 23327652, 2013). "However, not all studies have indicated a tumor inhibitory role for SDC-1 which appears to be pleiotropic depending on the tissue and cell of origin." (PMID 21655218, 2011). "Neither tumor nor stromal syndecan-1 correlated with Ki67 index (data not shown)." (PMID 18590537, 2008). "Interestingly, myeloma tumor cell‐derived shed SDC1 is uptaken by bone marrow stromal cells and is translocated to the nucleus, in an HS‐dependent manner, where it binds and inhibits histone acetyltransferase (HAT) p300 providing a mechanism for tumor–host cell crosstalk." (PMID 40542654, 2025).
tumor (continued). "Although HA does not bind Sdc-1 via direct interaction, these findings suggest that both molecules could interact functionally since they share several intracellular signaling pathways and have pleiotropic effects in tumor biology." (PMID 34070901, 2021). "However, although it seems likely that aberrant expression of syndecan-1 favors tumor progression, analysis of 51/55 patients in the survival study group revealed lack of significance between stromal syndecan-1 expression and survival (log rank test: p = 0.2765)." (PMID 32388727, 2020). "Thus, heparanase may influence the nuclear localization of syndecan-1 broadly throughout the tumor microenvironment, even within cells lacking heparanase expression." (PMID 19305494, 2009). "In this study, GSL I of SDC2, VVL of SDC1, and GSL II of MEC2 were stained only in tumor cells but not in vascular endothelial cells." (PMID 40844495, 2025). "The protein expression of MMP1, CD24, SDC1, and SPP1 was significantly correlated with tumor grade and subtype but not with tumor stage." (PMID 35037689, 2022). "Patients’ age, tumor stage, ECOG performance status, prior cystectomy (curative vs. palliative treatment groups), and distant metastases did not correlate with the SDC1 serum concentration." (PMID 33114033, 2020). "This contrasts sharply with the weak or absent correlation between tumor-infiltrating myeloid cells and expression of IL-34, PTPRZ1, and syndecan-1." (PMID 29796177, 2018). "Interestingly, we noted that WM-PC populations, sub-C7 (SDC1+TNFRSF17+) and sub-C11 (SDC1+CD3+), presented in low-tumor infiltration patients but were absent in high tumor infiltration ones." (PMID 36494694, 2022). "However, a follow-up study indicated that the major impact of syndecan-1 was not on Wnt signaling per se, but an alternate pathway that stabilized β-catenin/TCF-responsive tumor precursor cells." (PMID 33921767, 2021). "Therefore, circulating SDC1 and GPC4 might be markers of general organ dysfunction rather than specific tumor markers." (PMID 36353562, 2022). "However, whether nuclear SDC1 regulates the EMT process and tumor cell invasion is not known." (PMID 34208075, 2021).
cancer (329 papers, 2005 to 2026). A tumor composed of atypical neoplastic, often pleomorphic cells that invade other tissues. "To assess potential genomic alterations of SDC1 across cancers, we performed a pan-cancer analysis of its single-nucleotide variants (SNVs) and methylation status." (PMID 41364407, 2025). "Syndecan-1, a heparan sulfate proteoglycan, is another cell surface protein implicated in the regulation of lipid metabolism and cancer progression." (PMID 41303628, 2025). "SDC1 expression was associated with immune cell infiltration in almost all cancers by TCGA dataset, though this requires further validation." (PMID 41364407, 2025). "Dysregulation of syndecan-1, expressed in epithelial tissue, fibroblasts, and plasma cells, is associated with poor prognosis in several types of cancer." (PMID 39728992, 2024). "Syndecan-1 was found more in the tissue surrounding the tumors, and its presence was linked to how severe the cancer was." (PMID 39728992, 2024). "Recent studies have shown that soluble syndecan-1 (SDC1) serum level is an independent pre-operative predictor of cancer-specific survival in PCa, and SDC1 is associated with more aggressive tumors and a worse prognosis." (PMID 38240702, 2024). "SDC1, also known as CD138, is a marker for plasma cells that is closely associated with immunotherapy responses and survival in cancer patients." (PMID 37138324, 2023). "Researchers have found that high expression of SDC1 was significantly associated with adverse clinical outcomes of cancer." (PMID 36277284, 2022). "It has been suggested that shed SDC1 is associated with chemotherapy resistance, probably linking soluble SDC1 with poor survival of cancer patients." (PMID 36353562, 2022). "In fact, activated SDC1 shedding has been associated with increased metastasis in various cancers, indicating that soluble SDC1 represents a major facilitator for malignant cellular invasion." (PMID 36353562, 2022). "SDC1 overexpression in BC was found to promote cancer cell growth and proliferation and was associated with the methylation status of the SDC1 promoter." (PMID 36531485, 2022). "Activated shedding of membrane SDC1 and other HSPGs is mainly observed under various pathogenic conditions, including cancer." (PMID 36353562, 2022). "A loss of epithelial expression of syndecan-1 has been found to be an indicator of poor prognosis in many human cancers." (PMID 33437261, 2021). "In summary, this result confirms our experimental observation which indicates that Sdc-1 and HA are highly linked to proteins that participate in the activation of different signaling pathways playing an important role in cancer progression." (PMID 34070901, 2021). "Little is known regarding the regulation of syndecan-1 expression by mesenchymal cells, such as the cancer-associated fibroblast." (PMID 33921767, 2021). "Based on prior studies, specific associations between SDC-1 expression in different cells and cancer occurrence in different tissues cannot be made." (PMID 35118073, 2021). "SDC-1 is frequently misexpressed in cancer and associated with invasion, metastasis, angiogenesis, and dedifferentiation." (PMID 34976811, 2021). "Use of MMP inhibitors and A-TRA has been suggested in conjunction with chemotherapy to avoid the potentially severe side effects of cancer progression or recurrence caused by chemotherapy-induced SDC-1 shedding." (PMID 35118073, 2021). "High level of shed SDC-1 associates to cancer, infection and inflammation, thus our findings are in line with both previous and recent studies." (PMID 32731396, 2020). "SDC-1 is known, largely in the context of cancer metastasis to regulate cell proliferation with increased SDC-1 expression associated with higher cell proliferation." (PMID 32485953, 2020). "Syndecan-1 loss was later found to independently induce the EMT in several cancers, leading to increased migration and invasion." (PMID 33330449, 2020).
cancer (continued). "Recently, we have demonstrated that relative to non-IBC, carcinoma tissue of IBC confers a higher expression of Sdc-1 mRNA and protein that is associated with the expression of Notch as well as the unique cancer stemness phenotype of IBC." (PMID 31145753, 2019). "The loss of SDC1 expression in carcinoma cells reduces cell adhesion to the extracellular matrix and enhances cell motility and invasion." (PMID 31182980, 2019). "Our findings derive from a large, clinically annotated tissue microarray of CRC specimens and add to the body of evidence that the loss of epithelial SDC1 is a general feature of carcinoma progression." (PMID 31182980, 2019). "Because loss of membranous SDC1 increases the mobility of cancer cells, resulting in enhancement of metastasis, in general, loss or weak expression of SDC1 in tumors is thought to be associated with unfavorable outcomes." (PMID 30526845, 2018). "SDC1 expression varies between cancer types, but reduced expression in carcinomas is associated with enhanced cell motility and invasion." (PMID 30566430, 2018). "The prospective measurement of syndecan-1 on breast biopsies at diagnosis can potentially contribute to patient risk stratification toward tailored anti-cancer therapies." (PMID 28399903, 2017). "To investigate the involvement of Sdc1 in colitis-related carcinoma, we applied the AOM-DSS mouse model of colitis-associated cancer." (PMID 28350804, 2017). "The cancer-associated stroma showed significantly elevated syndecan-1 levels compared to normal stroma (p < 0.0001)." (PMID 27776346, 2016). "Dysregulated expression of Sdc1 has been reported in many types of cancers and been linked to cancer cell proliferation, invasion, metastasis, angiogenesis, and predicts poor prognosis." (PMID 26909794, 2016). "Syndecan-1 expression by CAFs has been reported in the progression of a number of cancers and has been implicated in ECM alignment." (PMID 27776346, 2016). "The identification and clinical validation of SDC1 as a new diagnostic and predictive biomarker will enable individualized therapeutic management for poor outcome cancer patients who are refractory to therapy or under high risk of relapse." (PMID 26293675, 2015). "The expression of SDC1 is dysregulated in cancer, and low expression of SDC1 in epithelial cells is associated with poor prognosis and high metastatic potential." (PMID 26293675, 2015). "In general, the loss of SDC1 expression in carcinoma cells reduces cell adhesion to the extracellular matrix and enhances cell motility and invasion." (PMID 26293675, 2015). "In prostate syndecan-1 was expressed in basolateral surface of normal epithelium, changing to a granular cytoplasmic expression pattern in carcinomas, a switch in subcellular expression pattern linked to EMT." (PMID 26420915, 2015). "Altered SDC-1 expression has been reported in a number of malignant tumor types and has been associated with differentiation status and survival." (PMID 24524203, 2014). "It was found that SDC1 was associated with malignant tumor metastasis and drug resistance." (PMID 37950222, 2023). "Due to the capacity of Sdc-1 to act as ligands or co-receptors for various signal-transducing receptors, affecting pathways associated with the hallmarks of cancer, namely proliferation, cell cycle, and apoptosis, we performed functional analysis related to these processes." (PMID 35155241, 2022). "In various types of cancer, Sdc1 deregulation has been linked to poor prognosis." (PMID 36009225, 2022). "In addition to an already broad range of physiological roles, SDC1 is also implicated in a multitude of pathological processes, including inflammation, wound healing, and cancer." (PMID 33801718, 2021). "Expression of SDC-1 may thus serve as a potential marker to identify patients predisposed to drug-resistant disease or metastasis on initial cancer diagnosis." (PMID 35118073, 2021).
cancer (continued). "Finally, both HPSE and Sdc-1 regulate the activity of pathways relevant to cancer progression, such as the stemness-associated Wnt pathway and metastasis-related focal adhesion kinase (FAK) signaling." (PMID 32477959, 2020). "Moreover, we have previously demonstrated that relative to non-IBC, carcinoma tissue of IBC confers a higher expression of Sdc-1 mRNA and protein that are associated with the unique cancer stemness phenotype of IBC." (PMID 31145753, 2019). "The in vitro silencing of syndecan-1 strongly destabilizes the holoclones by increasing ROS production, whereas in vivo syndecan-1 deficiency lowers the frequency of primitive cells expressing stem cell markers and markedly represses cancer propagation." (PMID 26273420, 2015). "In addition, increased expression of SDC1 in stromal fibroblasts is associated with angiogenesis and cancer progression." (PMID 26293675, 2015). "However, the concept of precision medicine can be implicated for specific cancer types, since higher or lower SDC1 expression is directly associated with more aggressive tumors and decreased patient survival in some cases." (PMID 26293675, 2015). "Moreover, loss of SDC1 expression in carcinoma was associated with poor differentiation and lymph node metastases." (PMID 26293675, 2015). "SDCs are widely recognized to undergo malignancy-associated changes in their expressions in several types of carcinomas, including those of thyroid, breast, colon, skin, stomach and urogenital tract, and SDC1 is recognized to be the best documented prognostic biomarker." (PMID 25935541, 2015). "In colorectal cancer, SDC1 expression was associated with stage and grade of cancer." (PMID 24373193, 2013). "High level of shed syndecan-1 is associated with infection, inflammation, and cancer." (PMID 24392351, 2013). "Accordingly, resistance of Syndecan-1-deficient mice to experimentally induced tumorigenesis has been linked to an alteration of Wnt-responsive precursor cell pools, demonstrating the essential role of Syndecan-1 cancer stem cell function in a mouse model." (PMID 24392029, 2013). "Loss of epithelial syndecan-1 is a general feature of carcinoma progression." (PMID 19865524, 2009). "Additionally, we found that this type of CAF was associated with cancer cells through the PTN-SDC1 axis, suggesting that SDC1 may be crucial in regulating CAFs in cancer cells." (PMID 39238647, 2024). "Furthermore, previous research has associated several adhesion molecules on cancer-associated fibroblasts, including syndecan-1 and DDR2, with the regulation of matrix organization and stiffness in BC and should be investigated on the HLFs conditioned via CM or EV-enriched solutions." (PMID 32429591, 2020). "Also, a shift of Sdc-1 from epithelial to stromal cells might attenuate the antimetastatic effect of Sdc-1 at the cancer cell surface where loss of its expression can promote EMT." (PMID 32477959, 2020). "SDC1 also plays a role in maintaining the osteo-adipogenic balance of human mesenchymal stem cells, but further experiment needs to be conducted to verify that SDC1 can induce cancer cell proliferation through stem cell formation." (PMID 41364407, 2025). "Second, the observed correlations between SDC1 expression and immune cell infiltration or cancer stemness remain preliminary; more mechanistic studies are needed to definitively establish the causal relationships in these processes." (PMID 41364407, 2025). "In contrast, Syndecan-1 detected high-grade cancer with precise labeling of poorly formed malignant glands." (PMID 41465218, 2025). "A bioinformatics analysis of SDC1's significant pro-cancer effects was conducted, and based on the findings, an in situ self-reactive gold nanocluster SDC1 shRNA-targeted nucleic acid delivery system was successfully constructed." (PMID 41209699, 2025). "Previous research has confirmed that Indatuximab ravtansine inhibits cancer cell growth by targeting SDC1." (PMID 40722759, 2025).